MMP9 (matrix metallopeptidase 9)
Diseases named in the same sentence as MMP9 in open-access papers (continued):
Sharing a sentence is not in itself a finding about the gene and the disease.
colorectal cancer (continued). "Taken together, these data suggest that in colorectal cancer cells, PlGF induces tumor cell invasion and migration through upregulation of MMP9 expression by increasing p38 phosphorylation." (PMID 23799978, 2013). "To investigate the clinical significance of this in vitro finding, we checked PlGF, Flt-1, and MMP9 expression in 80 human colorectal cancer tissues at the message level." (PMID 23799978, 2013). "This is a clear indication that MMP-2 is a key factor in the regulation of cell migration, however it should not be ruled out that other ECM degrading MMPs such as MMP-1, MMP-7, MMP-9 and MMP-13 have been shown be associated with Colorectal cancer progression." (PMID 24130681, 2013). "Plasmin activates pro-MMP-3 to MMP-3, which then activates pro-MMP-9 in the promotion of colorectal cancer progression." (PMID 23710449, 2013). "The role of MMP-9 immunoexpression in colorectal cancer is dual; it plays a role in matrix degradation enabling tumour invasion, but it also seems to act as a supportive factor for hosts’ defensive mechanisms against cancer spread." (PMID 23216739, 2012). "In this study, we studied the prognostic value of MMP-2, MMP-8 and MMP-9 immunoexpression in colorectal cancer." (PMID 23216739, 2012). "Previously we showed that MMP-2 in the intestinal mucosa of colorectal cancer patients is predominantly expressed in the submucosal extracellular matrix and MMP-9 in the mucosal macrophages and neutrophils." (PMID 22472880, 2012). "We studied the prognostic value of immunohistochemical expression of MMP-2, MMP-8, and MMP-9 in a series of 619 colorectal cancer patients using tissue microarray specimens." (PMID 23216739, 2012). "Stromal MMP-9 positivity also inhibits metachronous haematogenic metastasis in Dukes’ B and C colorectal cancer patients." (PMID 23216739, 2012). "MMP-2 and MMP-9 levels in normal mucosa are indicative of the course of disease in colorectal cancer patients." (PMID 22472880, 2012). "We assessed MMP-2 and MMP-9 levels in normal colorectal mucosa from colorectal cancer patients in relation to the course of the disease." (PMID 22472880, 2012). "In patients with colorectal cancer, MMP-9 expression in tumor tissue was found to be higher than that in healthy mucosa." (PMID 23276144, 2012). "The median protein level of MMP-2 and MMP-9 in the normal mucosa of the 198 colorectal cancer patients was 4.8 ng mg−1 protein (range, 0–30.5) for MMP-2 and 3.2 ng mg−1 protein (range, 0.2–164.7) for MMP-9." (PMID 22472880, 2012). "The aim of the present study was to evaluate the relation of the genotype and phenotype of MMP-2 and MMP-9 in normal appearing mucosa with outcome of patients with colorectal cancer." (PMID 22472880, 2012). "In the present study, we found high protein levels of MMP-2 and MMP-9 in mucosa adjacent to colorectal cancer tissue to be indicative for the course of disease, that is, independently associated with a worse survival of the patients." (PMID 22472880, 2012). "Here we show that MMP-9 tumour expression is an independent prognostic factor in Dukes’ B colorectal cancer." (PMID 23216739, 2012). "In the stage of cancer development, upregulation of MMP-2 and MMP-9 accelerates cell migration and invasion in colorectal cancer, thus resulting in the development of malignant tumor, poor prognosis, and shortening disease-free period and overall survival." (PMID 21859479, 2011). "Upregulation of MMP-2 and MMP-9 has been shown to play a key role in the progression, invasion, metastasis of colorectal cancer in animal models and patients." (PMID 21859479, 2011). "MMP-9 appears to be one of the most important since it is overexpressed in the majority of colorectal cancers." (PMID 19419554, 2009). "This study aims to evaluate the accuracy of serum MMP-9 as a test for colorectal cancer in a primary care population." (PMID 17076885, 2006).
colorectal cancer (continued). "This study will evaluate the accuracy of serum MMP-9 as a test for colorectal cancer in a primary care population, the target population for screening." (PMID 17076885, 2006). "A pilot study of patients attending a specialist clinic has indicated that serum MMP-9 is an accurate and acceptable test for colorectal cancer." (PMID 17076885, 2006). "Specifically in colorectal cancer, MMP-9 is derived principally from stromal monocytes and a high level of MMP-9 in tumor versus paired normal mucosa is an independent predictor of poor prognosis." (PMID 16168111, 2005). "The matrix metalloproteinases, MMP-2 and MMP-9, are capable of degrading components of the basement membrane, a vital barrier breached during the progression of colorectal cancer." (PMID 11401321, 2001). "TIMP-1 mRNA was detected in all 26 colorectal cancers examined, while only 18 out of 26 (69.2%) were positive for MMP-9." (PMID 7669564, 1995). "MMP-2 and MMP-9, members of the MMP family, are strongly linked to colorectal cancer metastasis." (PMID 40777130, 2025). "Reports suggest that dyscadherin/matrix metalloprotease 9 (MMP9) axis may be a viable therapeutic target for colorectal cancer (CRC) since it can accelerate the disease’s progression by altering TME through ECM remodeling." (PMID 40868987, 2025). "Notably, the matrix metalloproteinase (MMP) family, includes MMP9, which has been extensively explored for its critical contribution to the invasion and metastasis of colorectal cancer." (PMID 40595862, 2025). "AOPPs, NF-κB, and MMP-9 also demonstrated significant predictive value in colorectal cancer." (PMID 40729026, 2025). "This points to a clear gap in the research and indicates that the links suggested between MMP9, colorectal cancer, and neuropathy are, at this stage, hypotheses grounded in existing but separate pieces of evidence." (PMID 39664453, 2024). "In colorectal cancer, neutrophil-derived MMP-9 releases VEGF from the ECM by cleaving heparan sulfates, enhancing endothelial cell sprouting and angiogenesis, underlining MMP-9’s critical role in regulating VEGF bioavailability and its impact on tumor vascularization." (PMID 38693104, 2024). "In the phase of adenoma development, increased expression of MMP-1, MMP-3, MMP-7, and MMP-9 was observed, and subsequently, at the stage of colorectal cancer invasion, other MMPs, including MMP-2, MMP-8, MMP-10, MMP-12, MMP-13, MMP14, and MMP-21 are activated and overexpressed." (PMID 39337393, 2024). "The evidence suggests that MMP9 could act as a bridge between colorectal cancer and chronic CIPN development." (PMID 39664453, 2024). "The inhibition of MMP-9 improved sensitivity of colorectal cancer cells to 5-FU chemotherapy." (PMID 37143649, 2023). "The expression of MMP2 and MMP9 is related to the progression of colorectal cancer." (PMID 37492969, 2023). "Resveratrol is a polyphenol that downregulates the activity of the NF-κB signaling pathway to reduce the expression of the MMP-9 protein, and thus reduce the invasiveness of HepG2 cells and inflammatory responses in colorectal cancer cells treated with lipopolysaccharide (LPS)." (PMID 38005336, 2023). "Recently, angiopoietin-like protein 1 (ANGPTL1), which was detected in exosomes that were derived from human colorectal cancer cells, has been shown to inhibit the liver metastasis of colorectal cancer cells by blocking MMP9-induced vascular leakiness via the JAK2-STAT3 pathway." (PMID 37047335, 2023). "However, some researchers reported that MMP-2 is highly prognostic for colorectal cancer survival vs. MMP-9 as it is significantly increased in patients with lymph node metastasis compared to those without." (PMID 37509428, 2023). "Studies have also shown that high expression of eIF4E in invalids with colorectal cancer predict high risk of hepatic metastases and their related mechanism may be partly by the regulation of the levels of VEGF, cyclin D1, MMP-2, and MMP-9." (PMID 36118897, 2022).
colorectal cancer (continued). "CD276 impacts colorectal cancer cell migration through the Jak2/Stat3/MMP-9 signaling pathway." (PMID 35296518, 2022). "Additionally, exosomes derived from CD133+/CD44+ colorectal cancer cells after being transfected with sh-LINC01315 down-regulated BCL-2, MMP-9, and Vimentin, whereas up-regulated Bax, cleaved caspase-3, and E-cadherin in colorectal cancer cells (P < 0.05)." (PMID 35470736, 2022). "It was also revealed in similar research results that fentanyl could decrease miR-182 and MMP-9 generated by β-catenin to inhibit the growth and invasion of tumor cells for colorectal cancer." (PMID 35966857, 2022). "Moreover, we showed that the levels of 20S proteasomes in exosomes, MMP9+ and MMP9+/MMP2+/EMMPRIN+ exosome subpopulations in CD9-positive exosomes were significant for predicting colorectal cancer risk in CPPs." (PMID 33773551, 2021). "Moreover, in patients with Stage III colorectal cancer, the levels of 20S proteasomes (more than two units) and MMP9+ subpopulations (less than 60%) in plasma exosomes are favorable prognostic factors for overall survival." (PMID 34834058, 2021). "Hence, to investigate the molecular mechanism underlying GOFA-reduced MMP-9 expression in monocytic and colorectal cancer cells, we assessed the effects of specific inhibitors of MAPKs (ERK and p38) on LPS-induced migration and MMP-9 activity." (PMID 32492880, 2020). "Our results revealed that DUSP4 and Smad4 could regulate EMT of colorectal cancer through E-caderin, N-caderin, Vitmentin, and MMP9 gene." (PMID 32897241, 2020). "Previously in our study, we demonstrated that changes in serum concentrations of MMP-9 in patients with NSCLC during chemotherapy were intimately associated with chemotherapy outcome, which was in accordance with a previous study in colorectal cancer." (PMID 32377273, 2020). "IL-17, MMP-9 and CD23 were obviously related to TNM staging and differentiation degree of colorectal cancer, suggesting that the severity of colorectal cancer can be estimated by detecting the concentrations of IL-17, MMP-9 and CD23 in peripheral blood of patients in clinic." (PMID 32461933, 2020). "The cell-free supernatants of Lactobacillus sp., Lactobacillus casei, and Lactobacillus rhamnosus GG reduce metalloproteinase 9 (MMP-9) activity and increase the expression of a tight junction protein, zona occludens 1 (ZO-1), thereby inhibiting the invasiveness of colorectal carcinoma cells." (PMID 32238777, 2020). "In previous studies, we investigated the roles of MMPs including MMP2, MMP7, MMP8, MMP9 and MMP13 in the mice colorectal cancer model tissue, and observed that MMP7, MMP8, MMP9 are more important in colorectal cancer invasion and migration, and that MMP7 is regulated by NF-κB pathway." (PMID 31299935, 2019). "Thyroid hormone induces expression of MMP-2 and MMP-9 in myeloma cells and colorectal cancer cells." (PMID 30915033, 2019). "B. Detection of MMP8 and MMP9 in colorectal cancer cells with SREBP1 gene intervention." (PMID 31299935, 2019). "In addition, CCR1 knockdown significantly limits the activity and expression of matrix metalloproteinase-2 (MMP-2) and MMP-9, which predicts poor survival in colorectal cancer." (PMID 30979374, 2019). "Furthermore, MnTE-2-PyP effectively suppressed colorectal cancer cell migration and invasion and the expression of MMP-2 and MMP-9 caused by TGF-β." (PMID 30931081, 2019). "Increased MMP-9 serum concentration is of special interest in the progression of this cancer and might also play a role in the carcinogenesis from adenoma to colorectal carcinoma." (PMID 30154846, 2018). "Furthermore, an increase in MMP-9 expression was also seen around the budding cells at the invasive front of T1 colorectal carcinomas." (PMID 29731961, 2018). "We also proved that B7-H3 was co-expressed with MMP2 and MMP9 in colorectal cancer patients." (PMID 27145365, 2016).
colorectal cancer (continued). "Since CTHRC1 is expressed in several cancer models and has recently been implicated in vascular diseases, we hypothesized that CTHRC1 might regulate colorectal cancer tissue invasion and metastasis through modulation of MMP9." (PMID 24504172, 2014). "The correlation of high protein levels of MMP-2 and MMP-9 in mucosa adjacent to colorectal cancer tissue with worse survival, as we found, is probably also more, but not exclusively, related to endothelial cells in combination with epithelial cells and/or leukocytes." (PMID 22472880, 2012). "Overexpressions of MMP-2 and MMP-9 have been demonstrated in human colorectal cancers." (PMID 23300633, 2012). "We hypothesised that the expression of MMP-2 and MMP-9 in normal mucosa of colorectal cancer patients could be relevant as well to the outcome in colorectal cancer." (PMID 22472880, 2012). "Furthermore, NCTD downregulated MMP-9 promoter activity through the inhibition of Sp-1 transactivation in colorectal cancer cells." (PMID 22615870, 2012). "This study will establish the potential of serum MMP-9 as a screening test for colorectal cancer." (PMID 17076885, 2006). "Different studies showed that some MMP, including MMP2, MMP7 and MMP9 are expressed in colorectal adenomas that are well established premalignant lesions of colorectal cancers, implying their role other than extracellular matrix destruction and metastasis in cancer development and progression." (PMID 17125518, 2006). "MMP-9 (gelatinase B) is over-expressed in both breast and colorectal cancer." (PMID 12402142, 2002). "The aim of this study was to investigate whether immunohistochemical staining patterns of tissue inhibitor of metalloproteinases TIMP-2 and matrix metalloproteinases MMP-2 and MMP-9 can be predictors of tumour stage and survival time in colorectal cancer." (PMID 9310250, 1997). "However, the knockdown of the lncRNA STEAP3-AS1 significantly reduced the binding of BRG1, ERG, P300, and H3K18la, indicating that the lncRNA STEAP3-AS1-mediated BRG1/ERG/P300 complex regulates the H3K18la-specific activation of MMP9, which is a key to colorectal cancer liver metastasis." (PMID 40665344, 2025). "Finally, we evaluated whether PMPs can stimulate colorectal cancer cell invasiveness by enhancing MMP-2/MMP-9 levels and activity via the p38MAPK pathway." (PMID 36882818, 2023). "As in the case of colorectal cancer (CRC), cancer cells may display loss of polarity, epithelial markers such as E-cadherin, and upregulation of mesenchymal markers such as vimentin as well as metalloproteinases MMP2 and MMP9." (PMID 36072467, 2022). "Doxorubicin treatment has been shown to enhance MMP9 expression in H9c2 rat heart-derived embryonic myocytes, an effect that was reported to be mediated by p38 kinase, whereas NF-κB has been reported to promote MMP9 expression and 5′-fluorouracil resistance in colorectal cancer cell lines." (PMID 36010685, 2022). "Furthermore, the overexpression of CLDN-1 might be connected to MMP-9/Notch signaling to describe cellular proliferation in colorectal cancer." (PMID 33407452, 2021). "However, MMP2 and MMP9 were significantly related to colorectal cancer and could be regulated by Chinese medicine." (PMID 34381520, 2021). "A study showed that the expression of PCNA, Cyclin-D1, MMP-2, and MMP-9 genes can induce the formation of colorectal cancer and promote cancer cell proliferation, migration, and invasion, suggesting that these genes may be closely related to cell proliferation and migration." (PMID 32733959, 2020). "Thus, we explored the potential role of MMP-2 and MMP-9 in TGF-β-mediated EMT in colorectal cancer." (PMID 30931081, 2019). "Furthermore, MMP-2 and MMP-9 are induced by TGF-β in SW480 colorectal cancer cells." (PMID 30931081, 2019). "Furthermore, in patients with CRC, MMP-9 levels in adjacent tumor-free mucosa are elevated and this could be used as a predictor of 5-year relative survival in colorectal cancer." (PMID 29520667, 2018).
colorectal cancer (continued). "In addition, MMP1, MMP3 and MMP9 polymorphisms were not linked with colorectal cancer susceptibility." (PMID 28445160, 2017). "Thus, serum MMP-9 could be another valid marker of colorectal cancer progression, especially if combined with IL-8, (and CRP)." (PMID 22848630, 2012). "Interestingly, we previously observed that MMP-9 is involved in the VEGF-mediated neo-angiogenesis in colorectal cancer and that MMP-mediated endoglin mobilisation is involved in the regulation of the angiogenic potential of endothelial cells in colorectal cancer." (PMID 22472880, 2012). "The results indicate that the p-values of survival analysis for core genes IFNG, IL1B, and MMP9 are all less than 0.05, suggesting that in colorectal cancer patients, the high expression of IFNG, MMP9, and IL1B indicates a shorter survival time." (PMID 40868987, 2025). "Survival analysis of core genes suggests that high expression of IFNG, MMP9, and IL1B indicates a shorter survival time in colorectal cancer patients." (PMID 40868987, 2025). "In colorectal cancer, CXCR3 expression correlates with lymph node metastasis and poor prognosis, where CXCL10 enhances cell survival and invasion partly via matrix metalloproteinase-9 (MMP-9) upregulation." (PMID 41516196, 2025). "According to survival analysis of core genes, colorectal cancer patients with high levels of IFNG, MMP9, and IL1B expression are likely to have shorter survival times." (PMID 40868987, 2025). "In summary, this review has explored the relationship between colorectal cancer (CRC) and neuropathy, with a specific focus on chemotherapy-induced peripheral neuropathy (CIPN), highlighting the role of matrix metalloproteinase 9 (MMP9)." (PMID 39664453, 2024). "In colorectal cancer cells, quercetin lowered MMP-2 and MMP-9 activity, as confirmed by gelatin zymography." (PMID 39335164, 2024). "Mast cells have a pivotal role in the progression of colorectal cancer through the release of granules containing angiogenic factors such as VEGF-A, CXCL8, MMP-9, and lymphangiogenic factors like VEGF-C and VEGF-D." (PMID 38683136, 2024). "The insights from this review aim to expand our understanding and direct future research into the complex relationship between MMP9, CIPN, and colorectal cancer." (PMID 39664453, 2024). "In terms of miR-139-5p role in inflammation, overexpression of miR-139-5p was found to inhibit MMP9, MMP7, cell proliferation, and pro-inflammatory cytokines (IL-1β, IL-6, TNF-α) in colorectal cancer cell lines." (PMID 37474869, 2023). "GC-C signaling can also block metastasis by inhibiting matrix metalloproteinase-9 (MMP-9), which is produced by colorectal cancer cells." (PMID 38186653, 2023). "For instance, in a xenograft model of colorectal cancer, a pro-angiogenic monocyte subset was identified, defined by the expression of both CD14 and CD16 and the secretion of MMP-9, which exerted tumor-promoting functions." (PMID 37234993, 2023). "Curcumin has been reported to be an inhibitor of colorectal cancer invasion via AMPK-induced inhibition of NF-κB, urokinase-type plasminogen activator (uPA), and matrix metallopeptidase 9 (MMP-9)." (PMID 37298797, 2023). "For example, SAA1 produced by colorectal cancer cells recruits neutrophils to the invasive front of colorectal cancer, and stimulates neutrophils to produce CXCL8 and MMP-9, which contribute to tumor progression." (PMID 37081987, 2023). "Furthermore, the flavonoid abolished MMP-2 and MMP-9 activity in a concentration-dependent effect by suppressing pro-invasive Raf/PI3K signaling in murine colorectal carcinoma (CRC)." (PMID 37240168, 2023). "In colorectal cancer, miR-7 down-regulates the expression of paired box 6 (PAX6), which limits the PI3K/ERK-dependent up-regulation of MMP2 and MMP9 and hence inhibits colorectal cancer cell growth, proliferation, and metastasis." (PMID 36555120, 2022).